MYDGF (myeloid derived growth factor)
Description:
Bone marrow-derived monocyte and paracrine-acting protein that promotes cardiac myocyte survival and adaptive angiogenesis for cardiac protection and/or repair after myocardial infarction (MI). Stimulates endothelial cell proliferation through a MAPK1/3-, STAT3- and CCND1-mediated signaling pathway. Inhibits cardiac myocyte apoptosis in a PI3K/AKT-dependent signaling pathway (By similarity). Involved in endothelial cell proliferation and angiogenesis.
Synonyms: C19orf10; R33729_1; IL25; SF20; IL-25; IL-27; EUROIMAGE1875335; IL27; IL27w
Tractability: Antibody: UniProt places it where antibodies can reach, with high confidence; UniProt predicts a signal peptide or a membrane-spanning region; its Gene Ontology location is reachable by antibodies, with medium confidence. PROTAC: ubiquitination databases record sites on it; its protein half-life has been measured.
Gene: Protein-coding gene on chromosome 19 (4,641,374 to 4,670,365, reverse strand). Ensembl gene ENSG00000074842.
Subcellular location: Secreted; Endoplasmic reticulum-Golgi intermediate compartment; Endoplasmic reticulum; Golgi apparatus
Pathways (Reactome):
Cellular responses to stimuli: XBP1(S) activates chaperone genes
Gene Ontology:
Molecular function: protein binding
Biological process: positive regulation of angiogenesis; positive regulation of endothelial cell proliferation; negative regulation of apoptotic process; positive regulation of MAPK cascade; positive regulation of phosphatidylinositol 3-kinase/protein kinase B signal transduction; positive regulation of protein phosphorylation; positive regulation of transcription by RNA polymerase II
Cellular component: endoplasmic reticulum; endoplasmic reticulum-Golgi intermediate compartment; extracellular region; Golgi apparatus; endoplasmic reticulum lumen
Genetic constraint (gnomAD): Loss-of-function variants: 24 observed, 22.18 expected, observed/expected ratio (o/e) 1.08, 90% interval 0.78 to 1.52. The upper end of that interval is the gene's LOEUF score, 1.52, which puts it in group 6 of 6, group 1 being the genes least tolerant of losing a copy. Missense variants: 244 observed, 209.69 expected, observed/expected ratio (o/e) 1.16, 90% interval 1.05 to 1.29. Synonymous variants: 105 observed, 90.56 expected, observed/expected ratio (o/e) 1.16, 90% interval 0.99 to 1.36.
Homologues: Orthologues: chimpanzee MYDGF (100% identical), pig MYDGF (91% identical), macaque MYDGF (88% identical), mouse Mydgf (83% identical), rat Mydgf (81% identical), tropical clawed frog mydgf (49% identical), zebrafish mydgf (49% identical).
Diseases named in the same sentence as MYDGF in open-access papers:
MYDGF is named in the same sentence as 44 diseases in open-access papers, as found by Europe PMC text mining. Sharing a sentence is not in itself a finding about the gene and the disease. The quoted sentences say what the papers report.
myocardial infarction (13 papers, 2018 to 2025). Gross necrosis of the myocardium, as a result of interruption of the blood supply to the area, as in coronary thrombosis. "MYDGF was first detected in the heart after myocardial infarction, where it was shown to protect the heart and enhance its repair; it is produced by bone marrow-derived monocytes and macrophages." (PMID 40806387, 2025). "Its strong cardiomyocyte-protective and angiogenesis-promoting activities in myocardial infarction resulted in this protein being named myeloid-derived growth factor (MYDGF)." (PMID 40806387, 2025). "Myeloid-derived growth factor (MYDGF), a protein involved in the protection and repair of the heart after myocardial infarction was also identified in our analysis." (PMID 39194522, 2024). "Initially, MYDGF was found in bone marrow-derived monocytes and macrophages for cardioprotection and repair after myocardial infarction." (PMID 39030488, 2024). "The circulating concentration of hMYDGF in adults is approximately 3.3 ng/ml, and the plasma concentration of MYDGF is elevated during acute myocardial infarction and severe aortic stenosis." (PMID 39030488, 2024). "Myeloid-derived growth factor (MYDGF) is an endoplasmic reticulum protein of therapeutic interest because it promotes tissue repair in a murine model of myocardial infarction." (PMID 31819058, 2019). "We identified myeloid-derived growth factor (MYDGF), a protein previously identified in a secretome screen on human bone marrow cells and characterized in the context of myocardial infarct healing in mice and humans, as a mechanically-induced angiocrine signal." (PMID 38316785, 2024). "Previously, MYDGF has been reported to promote myocardial infarction repair via angiogenesis." (PMID 33391471, 2021). "C19orf10 was later found in bone marrow monocyte-macrophages expressing high levels of C-X-C motif chemokine receptor 4, and due to its potent cardiomyocyte-protective and angiogenic activity in myocardial infarction, it was formally named myeloid-derived growth factor (MYDGF)." (PMID 39030488, 2024). "Myeloid-derived growth factor (MYDGF) is a paracrine-acting protein that is produced by bone marrow-derived monocytes and macrophages to protect and repair the heart after myocardial infarction (MI)." (PMID 31772377, 2019).
atherosclerosis (5 papers, 2023 to 2025). A disease characterized by the build-up of fatty material and calcium deposition in the arterial wall resulting in partial or complete occlusion of the arterial lumen. "Bone marrow MYDGF-specific knockout mice exhibit severe endothelial damage, significantly increased inflammation, and increased susceptibility to atherosclerosis." (PMID 39030488, 2024). "The overexpression of MYDGF in bone marrow attenuates leukocyte influx into the aorta and prevents atherosclerosis onset via the downregulation of PKCδ/MAP4K4/NF-κB signaling." (PMID 40427505, 2025). "Subsequent studies have shown that MYDGF plays an important role in other cardiovascular diseases (e.g., atherosclerosis and heart failure), metabolic disorders, renal disease, autoimmune/inflammatory disorders, and cancers." (PMID 39030488, 2024). "Endothelial dysfunction is an early pathophysiological change in the development of atherosclerosis, and MYDGF has been shown to promote endothelial cell proliferation." (PMID 39030488, 2024). "Bone marrow transplantation or bone marrow-specific overexpression of MYDGF attenuated leukocyte homing in the aortas of atherosclerotic mice and ameliorated atherosclerosis by reducing inflammation and endothelial cell damage via the PKCδ/MAP4K4/NF-κB pathway." (PMID 39030488, 2024). "MYDGF inhibits MAP4K4 phosphorylation and decreases FOXO3a signaling and LDL transcytosis, rendering protection against atherosclerosis onset." (PMID 40427505, 2025).
hepatocellular carcinoma (5 papers, 2021 to 2025). A malignant tumor that arises from hepatocytes. "MYDGF may promote tumor angiogenesis and macrophage infiltration in hepatocellular carcinoma, releasing inflammatory cytokines, including IL-6 and TNF-α, which accelerate tumor progression." (PMID 40539074, 2025). "Serial analysis of gene expression showed that MYDGF was highly expressed in hepatocellular carcinoma (HCC), significantly and positively correlated with AFP, and promoted the proliferation of HCC cell lines through the AKT/MAPK pathway." (PMID 39030488, 2024).
bladder cancer (3 papers, 2021 to 2025). "Interestingly, MYDGF/C19orf10 is a protein promoting proliferation, migration, and invasion of bladder cancer cells, thereby contributing to the progression and malignant behavior of the disease by influencing pathways like PI3K/AKT and Wnt/β-catenin, as also suggested by our protein network." (PMID 41441336, 2025).
diabetic kidney disease (3 papers, 2021 to 2025). Progressive kidney disorder caused by vascular damage to the glomerular capillaries, in patients with diabetes mellitus. "Moreover, MYDGF deficiency led to more severe podocyte and glomerular injury and increased proteinuria in diabetic kidney disease (DKD) mice." (PMID 39030488, 2024).
heart failure (3 papers, 2024 to 2025). Inability of the heart to pump blood at an adequate rate to meet tissue metabolic requirements. "MYDGF may exert antifibrotic effects through the TGFβ1 pathway and inhibit the progression of heart failure." (PMID 39030488, 2024).
cardiac ischemia (2 papers, 2019 to 2021). "MYDGF-knockout mice, which lacked a developmental phenotype, developed larger infarct scars and impaired angiogenesis compared to control mice after cardiac ischemia followed by reperfusion." (PMID 31819058, 2019). "Delivery of recombinant mouse MYDGF also ameliorated effects of cardiac ischemia and improved survival of mice in which MYDGF was not knocked out7." (PMID 31819058, 2019).
colitis (2 papers, 2024). Inflammation of the colon. "MYDGF significantly alleviated DSS-induced colitis, suppressed lymphocyte infiltration, restored epithelial integrity in mice, and decreased apoptosis in the colon tissue." (PMID 38695882, 2024). "In addition, MYDGF enhance s the numbers and proportions of M2φ in a dextran sodium sulfate (DSS)−induced colitis model, and it decreases M1φ polarization while increasing M2φ polarization in primary Kupffer cells and in nonalcoholic fatty liver disease mouse model." (PMID 39497829, 2024).
liver cancer (2 papers, 2021). An epithelial or non-epithelial malignant neoplasm that arises from the liver. "MYDGF-mediated cell proliferation may be linked to its promotion of liver cancer stem cells (CSCs) self-renewal." (PMID 33391471, 2021).
liver dysfunction (2 papers, 2023 to 2025). "Here, patients and mice with NAFLD exhibited decreased circulating MYDGF levels and increased inflammation, metabolic disorders, and liver dysfunction." (PMID 37365185, 2023). "MYDGF has also been linked to the recurrence risk of non-alcoholic fatty liver disease (NAFLD), where its absence worsens liver index, lipogenesis, and liver dysfunction while restoring it mitigates these effects." (PMID 40539074, 2025).
rheumatoid arthritis (2 papers, 2007 to 2024). A chronic, systemic autoimmune disorder characterized by inflammation in the synovial membranes and articular surfaces. "MYDGF was identified in synovial fibroblast-like synovial cell proteins from patients with rheumatoid arthritis, which were distributed in the perivascular and synovial lining in synovial sections from rheumatoid arthritis and osteoarthritis patients." (PMID 39030488, 2024).
Allergy (1 paper, 2021). An allergy is an immune response or reaction to substances that are usually not harmful. "Further, two proteins involved in anti-inflammatory responses and tissue repair, TNFAIP3 and MYDGF respectively, were associated with lower risk of allergy development." (PMID 33722194, 2021). "Likewise, children with higher value of Interleukin (IL)-15 as well as TNFα-induced protein 3 (TNFAIP3) and Myeloid Derived Growth Factor (MYDGF) at 1 month had lower risk to develop allergy during the 8 year follow-up period." (PMID 33722194, 2021).
Arthritis (1 paper, 2021). Inflammation of a joint. "Myeloid-derived growth factor (MYDGF) is a 17-kDa secretory protein encoded by open reading frame 10 on human chromosome 19 20, which was reported to be highly expressed in synovial fluid during arthritis, suggesting a correlation between its secretion and joint inflammation." (PMID 33391471, 2021).
chronic kidney disease (1 paper, 2025). Impairment of the renal function secondary to chronic kidney damage persisting for three or more months. "Myeloid‐derived growth factor (MYDGF) is decreased in proximal tubules from patients with chronic kidney disease (CKD) and correlates with key factors related to kidney fibrosis and estimated glomerular filtration rate." (PMID 39587987, 2025).
coronary artery disease (1 paper, 2022). "The biological function of MYDGF is relatively unknown; however, previous studies in mouse models of coronary artery disease have demonstrated that monocytes and macrophages secrete MYDGF as a protective and reparative response following myocardial infarction." (PMID 35197532, 2022).
diabetes (1 paper, 2023). "Thus, MYDGF may be a therapeutic drug for NAFLD, and bone marrow may serve as a therapeutic target for metabolic disorders such as NAFLD, obesity, and diabetes." (PMID 37365185, 2023).
eosinophilia (1 paper, 2024). "MYDGF is produced by mucosal epithelial cells, and when it is overly expressed, it promotes eosinophilia and triggers the production of TH2-type cytokines." (PMID 38400120, 2024).
Hepatic steatosis (1 paper, 2023). Steatosis is a term used to denote lipid accumulation within hepatocytes. "In conclusion, we have successfully demonstrated that MYDGF alleviates inflammation, lipogenesis, and hepatic steatosis in a manner involving IKKβ/NF-κB signaling." (PMID 37365185, 2023).
Insulin resistance (1 paper, 2023). Increased resistance towards insulin, that is, diminished effectiveness of insulin in reducing blood glucose levels. "Our recent study suggested that myeloid-derived growth factor (MYDGF) improves insulin resistance." (PMID 37365185, 2023).
ischemic disease (1 paper, 2019). Lack of blood supply to an area of the body, resulting in impairment of tissue oxygenation. "The potential of MYDGF to positively affect other ischemic diseases needs to be evaluated and would help to obtain a more complete understanding of the breadth of it’s therapeutic applications." (PMID 31772377, 2019).
kidney damage (1 paper, 2025). "Considering that tubular atrophy and tubulointerstitial fibrosis have been proven to be reliable features for the prediction of progression to end‐stage kidney disease, our results suggest that MYDGF might be a potential biomarker for CKD and predict the progression of kidney damage." (PMID 39587987, 2025).
lipid metabolism disorders (1 paper, 2025). "Studies have shown that MYDGF knockout diabetic mice exhibit raised concentrations of total cholesterol, triglycerides, and free fatty acids, indicating that the absence of MYDGF leads to lipid metabolism disorders." (PMID 40539074, 2025).
Obesity (1 paper, 2023). Accumulation of substantial excess body fat. "Considering that macrophages have been implicated to critically determine the development and progression of obesity-associated NAFLD, it is necessary to address how MYDGF in macrophages alters certain aspects of NAFLD." (PMID 37365185, 2023).
steatosis (1 paper, 2023). Increased lipid within the cytoplasm of cells. "As shown by these data, MYDGF deficiency in myeloid cells exacerbated lipogenesis and steatosis in NAFLD mice." (PMID 37365185, 2023). "Here, we found that myeloid cell-specific MYDGF deficiency aggravated hepatic inflammation, lipogenesis, and steatosis, and show that myeloid cell-derived MYDGF restoration alleviated hepatic inflammation, lipogenesis, and steatosis." (PMID 37365185, 2023). "We were next interested in assessing the extent of hepatic inflammation, lipogenesis, and steatosis after myeloid cell MYDGF restoration in KO mice." (PMID 37365185, 2023).
xerostomia (1 paper, 2024). Dryness of the mouth resulting from reduced salivary secretion. "Further research is required to determine whether MYDGF can be used as an alternative cell-free therapy to alleviate xerostomia in patients with pSS." (PMID 39497829, 2024).
tumor (10 papers, 2021 to 2025). "MYDGF was ultimately selected as the primary biomarker for further investigation due to its association with poor prognosis, high tumor expression, and superior predictive capability." (PMID 40539074, 2025). "Considering aberrant angiogenesis in tumor progression, we explored the role of MYDGF during this pathogenic process." (PMID 33391471, 2021). "While all proteins, as expected, were correlated with tumor stage according to proteomic data, GANAB, THIC/ACAT2, SEPT8, PPIA, and GALE showed an inverse correlation with tumor size, whereas MYDGF displayed a positive correlation." (PMID 41441336, 2025). "CytoTRACE analysis revealed a significant increase in tumor stemness features in the MYDGF+ group compared to the MYDGF- group." (PMID 40539074, 2025). "MYDGF has potent anti-apoptotic and tissue repair effects on many diseases, however, these beneficial effects in cancer promote tumor cell development and further deterioration." (PMID 39030488, 2024). "Hepatocellular carcinoma contains hypoxia-induced MYDGF in its cytoplasm and cell membrane, which can stimulate tumor angiogenesis and boost the potential of cancer stem cells to self-renew." (PMID 36071472, 2022). "At the end of the experiment, gene expression level of MYDGF in tumor tissues was confirmed, and the knockdown efficiency remained above 70%." (PMID 33391471, 2021). "Paired HCC primary tumor and paracancerous samples revealed that MYDGF was higher in HCC both transcriptionally and translationally (p < 0.001)." (PMID 33391471, 2021). "Here, we observed that MYDGF expression was higher in M1 stage relative to M0 stage, suggesting MYDGF accumulation with tumor malignant and metastatic state." (PMID 33391471, 2021). "IHC analysis of Ki67 and PCNA in tumor tissues revealed that proliferation was markedly reduced in the MYDGF knockdown group (p < 0.05)." (PMID 33391471, 2021). "Tumor angiogenesis, immune cell infiltration, macrophage chemotaxis and inflammatory cytokines detection were utilized to clarify how MYDGF remodeled the tumor microenvironment (TME) to accelerate the progress of HCC." (PMID 33391471, 2021). "Furthermore, the abundance of proteins such as GANAB, GALE, THIC, SEPT8, and MYDGF/C19orf10 correlated with tumor size, suggesting their potential as prognostic biomarkers." (PMID 41441336, 2025). "S100A9, which we found up-regulated in pT1-HG biopsies, was identified as a protein associated with iNOS activity, and it is also involved in the regulation of signal transduction, such as SOD2, APOA1, HSP90, HSPA5, HINT1, MYDGF, and SerpinB3, and in immunomodulation in tumor microenvironments." (PMID 41441336, 2025). "On the other hand, MYDGF/C19orf10 was positively correlated with tumor size." (PMID 41441336, 2025). "MYDGF can promote self-renewal of liver tumor stem cells and tumor angiogenesis, induce macrophage chemotaxis into tumor tissues and release a variety of inflammatory factors, which ultimately aggravate inflammation in the tumor microenvironment and accelerate HCC progression." (PMID 39030488, 2024). "However, the molecular mechanism of MYDGF action in tumor progression is still unclear, and it merits further research." (PMID 36071472, 2022). "Additionally, tumor-derived MYDGF promotes the release of inflammatory cytokines including TNF-α and IL-6 and increases macrophage infiltration, all of which ultimately aid in the growth of tumors." (PMID 36071472, 2022). "Previous studies suggested that MYDGF played a role in regeneration 24 while stem-like properties could accelerate tumor cell proliferation 25-29." (PMID 33391471, 2021). "Here, we found that MYDGF could induce macrophages chemotaxis and secretion of inflammatory cytokines by macrophages, indicating that MYDGF might remodel the tumor microenvironment to accelerate HCC progression." (PMID 33391471, 2021).